RAB23 (RAB23, member RAS oncogene family)
Description:
The small GTPases Rab are key regulators of intracellular membrane trafficking, from the formation of transport vesicles to their fusion with membranes. Rabs cycle between an inactive GDP-bound form and an active GTP-bound form that is able to recruit to membranes different set of downstream effectors directly responsible for vesicle formation, movement, tethering and fusion. In conjunction with IFT57 and KIF17, it drives the localization of specific G protein-coupled receptors, such as the dopamime receptor DRD1, to primary cilia. Has a critical role in the formation and elongation of neuronal primary cilia, thereby impacting the activation of sonic hedgehog (Shh) signaling. Additionally, it is involved in the down-regulation of Shh signaling by cooperating with SUFU to prevent the nuclear import of GLI1 transcription factor, thus suppressing its transcriptional activity. Regulates GLI1 in differentiating chondrocytes. Likewise, regulates GLI3 proteolytic processing and modulates GLI2 and GLI3 transcription factor activity. Plays a role in autophagic vacuole assembly, and mediates defense against pathogens, such as S.aureus, by promoting their capture by autophagosomes that then merge with lysosomes.
Synonyms: HSPC137; CRPT1
Tractability: Small molecule: a structure with a bound ligand is known. Antibody: its Gene Ontology location is reachable by antibodies, with high confidence; UniProt places it where antibodies can reach, with medium confidence; the Human Protein Atlas places it where antibodies can reach. PROTAC: ubiquitination databases record sites on it; its protein half-life has been measured.
Gene: Protein-coding gene on chromosome 6 (57,186,992 to 57,222,848, reverse strand). Ensembl gene ENSG00000112210.
Subcellular location: Cell membrane; Cytoplasm; Cytoplasmic vesicle, autophagosome; Endosome membrane; Cytoplasmic vesicle, phagosome; Cytoplasmic vesicle, phagosome membrane
Subcellular location (Human Protein Atlas): Cytosol; Plasma membrane; Basal body; Centrosome; Primary cilium
Pathways (Reactome):
Metabolism of proteins: RAB geranylgeranylation
Gene Ontology:
Molecular function: G protein activity; GTPase activity; protein binding; GTP binding
Biological process: autophagosome assembly; cellular defense response; cilium assembly; craniofacial suture morphogenesis; GTP metabolic process; negative regulation of protein import into nucleus; negative regulation of smoothened signaling pathway; regulation of protein localization; anatomical structure morphogenesis; regulation of smoothened signaling pathway; system development
Cellular component: autophagosome; cytoplasm; cytosol; phagocytic vesicle; plasma membrane; endosome membrane; cytoplasmic vesicle; phagocytic vesicle membrane
Genetic constraint (gnomAD): Loss-of-function variants: 11 observed, 21.72 expected, observed/expected ratio (o/e) 0.51, 90% interval 0.32 to 0.84. The upper end of that interval is the gene's LOEUF score, 0.84, which puts it in group 3 of 6, group 1 being the genes least tolerant of losing a copy. Missense variants: 194 observed, 235.63 expected, observed/expected ratio (o/e) 0.82, 90% interval 0.73 to 0.93. Synonymous variants: 78 observed, 78.58 expected, observed/expected ratio (o/e) 0.99, 90% interval 0.83 to 1.2.
Gene-disease validity (ClinGen):
ClinGen rates the evidence that RAB23 causes each of these diseases.
RAB23-related Carpenter syndrome (autosomal recessive): Definitive. Any Carpenter syndrome in which the cause of the disease is a mutation in the RAB23 gene.
Homologues: Orthologues: chimpanzee RAB23 (99% identical), macaque RAB23 (99% identical), dog RAB23 (97% identical), rat Rab23 (94% identical), mouse Rab23 (93% identical), guinea pig RAB23 (92% identical), zebrafish rab23 (84% identical), pig RAB23 (82% identical), rabbit RAB23 (81% identical), tropical clawed frog rab23 (69% identical), Drosophila melanogaster Rab23 (57% identical). Paralogues in human: RAB5A (29% identical), RAB7A (29% identical), RAB5B (29% identical), RAB6B (29% identical), RAB29 (28% identical), RAB5C (28% identical), RAB6A (28% identical), RAB34 (28% identical), RAB35 (28% identical), RAB7B (28% identical), RAB9B (28% identical), RAB36 (27% identical), and 56 more.
Diseases named in the same sentence as RAB23 in open-access papers:
RAB23 is named in the same sentence as 53 diseases in open-access papers, as found by Europe PMC text mining. Sharing a sentence is not in itself a finding about the gene and the disease. The quoted sentences say what the papers report.
Carpenter syndrome (19 papers, 2008 to 2025). An extremely rare autosomal recessive syndrome characterized by premature closure of cranial sutures leading to cone-shaped head, fusion of the digits, and the presence of more digits than normal. "Carpenter syndrome (CS) is a pleiotropic autosomal recessive genetic disorder often reported in patients carrying biallelic pathogenic variants in RAB23." (PMID 40825043, 2025). "RAB23 mutations lead to Carpenter syndrome (CS), which manifests multiple clinical features resembling those of ciliopathies, a spectrum of disorders caused by defective primary cilia." (PMID 40825043, 2025). "Our work thus provides compelling and direct evidence demonstrating that RAB23 mutation is clinically linked to ciliopathy, further validating the classification of Carpenter syndrome as one of the disorders within the ciliopathy spectrum." (PMID 40825043, 2025). "Mutations of RAB23 in humans lead to Carpenter syndrome (CS), an autosomal recessive disorder clinically characterized by craniosynostosis, polysyndactyly, skeletal defects, obesity, and intellectual disability." (PMID 40825043, 2025). "The elusive pathogenesis of CKD in Carpenter syndrome beckons further exploration, necessitating a deeper investigation into the specific mechanisms connecting RAB23 mutations to CKD." (PMID 39040725, 2024). "The discovery of a homozygous mutation in the RAB23 gene underscores its role in Carpenter syndrome and the sonic hedgehog signaling pathway." (PMID 39040725, 2024). "Carpenter syndrome, or acrocephalopolysyndactyly type II, is a rare autosomal recessive disorder associated with biallelic mutations in RAB23." (PMID 39040725, 2024). "In humans, mutations in the Rab23 gene are directly implicated in Carpenter syndrome, a developmental disorder associated with developmental abnormalities such as cranial deformity, extra and short fingers or toes." (PMID 39615683, 2024). "Genetic mutations in RAB23 can cause Carpenter syndrome (CS), a rare autosomal recessive disorder characterized by craniofacial defects, polydactyly, cardiac defects, craniosynostosis, and obesity." (PMID 39451207, 2024). "The structural changes potentially disrupted the binding of Rab23 Y79del to its interacting partners, thus leading to a loss-of-function and the development of Carpenter syndrome." (PMID 39615683, 2024). "Carpenter syndrome, characterized by RAB23 mutations, is a rare autosomal recessive disorder distinguished by unique features such as craniofacial anomalies, congenital heart disease, brachydactyly, and obesity." (PMID 39040725, 2024). "Carpenter syndrome–associated mutations in the Rab23 gene reported to date include missense point mutations, in-frame deletions, and truncating mutations." (PMID 39615683, 2024). "Several Rab23 mutants are clinically identified to be associated with Carpenter syndrome: three point mutations, M12K, C85R, and Y79 deletion (Y79del), are situated in the GTPase domain." (PMID 39615683, 2024). "To obtain structural insights into the pathogenesis of Carpenter syndrome implicating mutated Rab23, we determined crystal structures of a clinically relevant hRab23 mutant carrying a Tyr79 deletion (Y79del), in complex with GDP and GMPPNP, respectively." (PMID 39615683, 2024). "Mutations in Rab23 are directly implicated in Carpenter syndrome, a development disorder characterized by deformed skulls, abnormal fingers or toes, and intellectual disabilities." (PMID 39615683, 2024). "Mutations in RAB23 cause Carpenter syndrome, a condition that affects normal organogenesis and patterning." (PMID 36910145, 2023). "Carpenter syndrome is often caused by changes to the gene responsible for making a protein called RAB23." (PMID 32662771, 2020).
Carpenter syndrome (continued). "Mutations in the gene encoding Ras-associated binding protein 23 (RAB23) cause Carpenter Syndrome, which is characterized by multiple developmental abnormalities including polysyndactyly and defects in skull morphogenesis." (PMID 32662771, 2020). "Similar to Carpenter syndrome patients, RAB23 deficient mice exhibited polysyndactyly and multiple craniosynostoses." (PMID 32662771, 2020). "Rab23 is mutated in Carpenter syndrome, an autosomal recessive human developmental disorder characterized by open neural tube and craniofacial defects." (PMID 31564489, 2019). "Notwithstanding these considerations, most patients with Carpenter syndrome reported to date are homozygous for truncating (nonsense or frameshift) mutations in RAB23." (PMID 21412941, 2011). "Carpenter syndrome manifests polysyndactyly and craniosynostosis, with mental retardation and has recently been shown to be caused by mutations in the RAB23 gene." (PMID 18435847, 2008). "However, as far as our current knowledge extends, there remains a lack of direct evidence substantiating the causal link between RAB23 mutation and Carpenter syndrome with ciliopathy." (PMID 40825043, 2025). "Importantly, the Rab23 loss-of-function mouse mutants serve as a robust disease model for Carpenter syndrome, as they successfully recapitulate numerous clinical characteristics observed in human patients." (PMID 40825043, 2025). "Pathogenic SNVs in RAB23 are associated with Carpenter Syndrome (CS) a rare genetic disorder characterized by craniosynostosis of the face and skull, polydactyly, brachydactyly, heart and eye defects, structural and functional central nervous system (CNS) abnormalities (OMIM #201000)." (PMID 40395934, 2025). "Our data reveals for the first time that Carpenter syndrome patients carrying the biallelic RAB23 p.(L145*) variant exhibit variable degrees of primary cilia anomalies in their tissue samples-derived iPSCs, iPSC-differentiated neurons, neural progenitor cells and fibroblasts." (PMID 40825043, 2025). "Homozygous null mutations in the Rab-GTPase, RAB23, lead to Carpenter syndrome." (PMID 36568981, 2022). "Similarly, recessive Rab23 nonsense mutations in the open brain mouse are embryonically lethal due to open neural tube defects and other changes reminiscent of Carpenter syndrome." (PMID 31564489, 2019). "Carpenter syndrome, a rare autosomal recessive disorder characterized by a combination of craniosynostosis, polysyndactyly, obesity, and other congenital malformations, is caused by mutations in RAB23, encoding a member of the Rab-family of small GTPases." (PMID 21412941, 2011). "The identification of a homozygous missense mutation (p.M12K) and a homozygous amino acid deletion (p.Y79del) in RAB23, which were both associated with fairly typical features of Carpenter syndrome, highlights two residues important for normal biochemical function." (PMID 21412941, 2011). "This study unveils that conditional knockout mouse mutants of Rab23 exhibit a spectrum of phenotypic and pathological traits reminiscent of the classical clinical features reported in both Carpenter syndrome and ciliopathy disorders in humans." (PMID 40825043, 2025). "Taken together, the Rab23 mutants prominently display multiple developmental features that closely resemble both Carpenter syndrome patients and individuals affected by other forms of ciliopathy." (PMID 40825043, 2025). "Mutations in RAB23 cause Carpenter syndrome (CS), which is characterized by developmental defects in the heart, neural tube, and skeleton (MIM# 201000, Acrocephalopolysyndactyly type II)." (PMID 40261407, 2025). "The significance of this finding lies in the role of RAB23 as a critical negative regulator of the sonic hedgehog signalling pathway, underscoring the genetic underpinnings of Carpenter syndrome." (PMID 39040725, 2024).
Carpenter syndrome (continued). "In humans, loss-of-function mutation of RAB23, member RAS oncogene family (RAB23) leads to Carpenter syndrome with multi-suture synostosis, polysyndactyly, obesity and cardiac defects." (PMID 35451466, 2022). "Commonality of etiological mechanisms is suggested by the overlapping skeletal phenotypes exhibited in Carpenter syndrome and Grieg cephalopolysyndactyly syndrome patients as well as their mouse disease models, Gli3Xt−J/Xt−J and Rab23-/- (this study)." (PMID 32662771, 2020). "Strikingly, both the global gene knockout (KO) mutants (actin-Cre), and neural progenitor cells (NPCs)-specific knockout mutants of Rab23 display a range of developmental and phenotypic abnormalities that largely resemble the clinical features observed in Carpenter syndrome and ciliopathy patients." (PMID 40825043, 2025). "Additionally, akin to the observations in the human NPCs derived from the Carpenter syndrome patient iPSCs, the cortical NPCs cultured from Rab23-KO mice also exhibit a shortened cilia length." (PMID 40825043, 2025). "In RAB23-deficient mice, which mimic Carpenter syndrome in humans, the lack of functional RAB23 results in overt FGF10, Hh and Nodal signaling with consequent misexpression of downstream signal transducers (pERK1/2, Gli1, Lefty1/2 and Pitx2)." (PMID 40261407, 2025). "Carpenter syndrome is associated with variations in RAB23 gene; however, the sibling’s genes did not exhibit this variation." (PMID 34348791, 2021). "We hypothesize that the decrease in ciliation disrupts the signal transduction of primary cilium-dependent Shh signaling pathway, potentially playing a role in the phenotypical abnormalities and developmental defects observed in the Rab23-KO mutant and Carpenter syndrome patients." (PMID 40825043, 2025). "RAB23 regulates growth factor signaling, and mutations in RAB23 affect the development and patterning of multiple organs and give rise to a diverse complex congenital anomaly, collectively known as Carpenter syndrome (CS, MIM# 201000) or acrocephalopolysyndactyly type II." (PMID 36910145, 2023).
hepatocellular carcinoma (10 papers, 2012 to 2024). A malignant tumor that arises from hepatocytes. "As an oncogene, Rab23 has been shown to be significantly related to the growth and migration of hepatocellular carcinoma in both in vitro and in vivo studies, but its underlying mechanism remains obscure." (PMID 37884351, 2024). "It emerges as a key orchestrator in the EMT process, with research indicating its role in inhibiting hepatocellular carcinoma cell migration by targeting RAB23 and reversing EMT." (PMID 38662949, 2024). "Rab23 knockdown hepatocellular carcinoma cell line was generated through lentiviral transduction, then we established a nude HCC xenograft model by subcutaneously implanting the transfected cells." (PMID 37884351, 2024). "It is reported that RAB23 take a vital part in the tumorigenesis of several cancer types, such as hepatocellular cancer, squamous cell carcinoma, and prostate cancer." (PMID 37935937, 2023). "Rab23 promotes hepatocellular carcinoma cell migration via the Rac1/TGF-β signaling pathway and promotes squamous cell carcinoma cell migration and invasion by regulating the integrin β1/Tiam1/Rac1 pathway." (PMID 32605180, 2020). "Among them RAB23, found to be up-regulated in this study, has been shown to be over-expressed and/or activated in hepatocellular carcinoma." (PMID 22724020, 2012). "Furthermore, we investigated the impact of Rab23 knockdown on apoptosis levels in hepatocellular carcinoma cell lines using flow cytometry." (PMID 37884351, 2024). "In addition, Li et al25 discovered that circMYLK can promote the growth and metastasis of hepatocellular carcinoma by sponging miR‐362‐3p and increasing Rab23 expression." (PMID 32342645, 2020). "These experimental results present new evidence for the mechanisms of Rab23 on HCC, which will help to improve the development of therapeutic strategies for patients with hepatocellular carcinoma." (PMID 37884351, 2024). "Rab23 is a member of the Ras-related small GTPase family, which can activate Rac1-TGFβ signal transduction and promotes EMT in hepatocellular carcinoma (HCC) cells." (PMID 38791951, 2024). "In hepatocellular carcinoma (HCC), inhibition of Rab23, a protein belonging to the Rab family of GTPases, negatively regulates the Shh signalling pathway and decreases the expression, nuclear translocation and localisation of Gli1 via GDP/GTP binding." (PMID 29899399, 2018).
craniosynostosis (9 papers, 2008 to 2025). Craniosynostosis is defined as the premature fusion of one or more cranial sutures leading to secondary distortion of skull shape resulting in skull deformities with a variable presentation. "Mutations in other HH pathway members such as Ptch1, Smo, Gli3, and Rab23 also cause craniosynostosis in humans and/or mice." (PMID 34880220, 2021). "RAB23 encodes a small GTPase that is a negative regulator of hedgehog signalling and loss of RAB23 function causes excessive hedgehog signalling resulting in craniosynostosis and polydactyly." (PMID 38760421, 2024). "Craniosynostosis is a nearly universal feature in cases of both RAB23- and MEGF8-associated CRPTS." (PMID 38760421, 2024). "Originally described in 1901 in a family with craniosynostosis and polysyndactyly, the most common form of CRPTS (CRPT1; OMIM 201000) was shown in 2007 to be caused by biallelic pathogenic variants in RAB23." (PMID 38760421, 2024). "Rab23-/- mice at embryonic day E18.5 exhibited craniosynostosis in the coronal, parietal-temporal, fronto-nasal and in the lambdoid sutures when compared to their wild type (Wt) littermates." (PMID 32662771, 2020). "Along with craniosynostosis, Rab23-/- mice showed skeletal patterning defects in the forelimbs and hindlimbs." (PMID 32662771, 2020). "Polydactyly and craniosynostosis were observed (100%) in all Rab23-/- samples examined." (PMID 32662771, 2020). "On the other hand, it would be important to include other genes, such as TCF12 (OMIM 600,480), MSX2 (OMIM 123,101), RAB23 (OMIM 606,144), and EFNB1 (OMIM 300,035), to determine their participation in craniosynostosis in the Mexican population." (PMID 32510873, 2020).